TNF (tumor necrosis factor)
Diseases named in the same sentence as TNF in open-access papers (continued):
Sharing a sentence is not in itself a finding about the gene and the disease.
liver disease (continued). "In addition, H. pylori infection might worsen the liver functions and portal hypertension through overproduction of proinflammatory cytokines such as tumor necrosis factor-α, interleukins, nitric oxide, and endothelin-1." (PMID 30881448, 2019). "However, c-Jun N-terminal kinase (JNK) inhibition or Bim deletion did not fully rescue the cells from TNF-induced apoptosis sensitization indicating there must be another crosstalk between TNFα- and FasL-induced signaling, which increases hepatocyte cell death and contributes to liver diseases." (PMID 30185788, 2018). "HCV replication, instead, enhances the NFκB pathway activation triggered by tumor necrosis factor-alpha (TNFα); thus the low Zn plasma levels may prompt the onset of an inflammatory environment known to play a key role in virus-related liver disease progression." (PMID 24371505, 2013). "Our data demonstrate that in hepatic cancer cell lines APE1 redox function is involved in TNF-α and FA-induced IL-8- and IL-6 expression, and its inhibition by E3330 may represent a promising tool for reducing the early inflammatory process in liver diseases such as in NASH." (PMID 23967134, 2013). "Furthermore, the rate of progression of CHC to end-stage liver disease might be related to an up-regulation of the TNF-α/Fas pathways." (PMID 20051112, 2010). "Therefore, the excess number of mast cells in the small bowel and in the mesenteric lymph node complex of rats with portal hypertension could be related to their ability to release the stored TNF-α when the appropriate stimulus is acting." (PMID 17999758, 2007). "In addition, proinflammatory cytokines (IL-1, IL-6, IL-23, TNF) and the imbalance in T-cell subtypes, such as T helper 17/T regulatory cell, promote hepatic inflammation and induction of fibrosis, leading to the potential development and progression of liver disease." (PMID 41209843, 2026). "Previous researches have demonstrated that gut microbiota can modulate the release of IL-6, TNF-α, hepatocyte growth factor (HGF), IFN-γ and TGF-β, which are involved in liver regeneration and different liver disorders." (PMID 41333471, 2025). "Further analysis of predicted upstream regulators in KO mice suggested that reduced immune cell activation (TNFα–NF-kB complex) and reduced stellate cell activation (TGFβ1–SMAD3) contribute to KO-mediated protection against alcohol-induced liver disease." (PMID 40824250, 2025). "Overall, this meta-analysis found some evidence for an association between TNF-α rs361525 and IFN-γ rs2430561 polymorphisms and the risk of LC suggesting that they may represent viable targets for clinical research aimed at predicting the future risk of severe liver disease." (PMID 37122734, 2023). "However, its diagnostic value is limited as albumin levels may be influenced by various factors, including liver disease, gastrointestinal and renal losses, and inflammatory states characterized by high levels of tumor necrosis factor-alpha (TNF-α) and interleukin 6 (IL-6)." (PMID 38021540, 2023). "Pro-inflammatory cytokines, such as tumor necrosis factor (TNF)-α and interleukin (IL)-6, play essential roles in the development of various inflammatory liver diseases that result in liver cirrhosis." (PMID 37895873, 2023). "Hepatic pyroptosis controls IL-1β production, which has been reported to promote the production of other proinflammatory cytokines (such as TNF-α and MCP-1) and aggravate the inflammatory response in liver disease." (PMID 38090607, 2023). "IL-6, TNF-α, and TGF-β1 are important inflammatory factors in the inflammatory response of the liver and are involved in a variety of liver diseases." (PMID 35629298, 2022). "In this study we found that Bcl-3 promotes TNF-induced hepatocyte apoptosis by enhanced RIP1 deubiquitination, providing a novel Bcl-3-targeted strategy for various liver diseases." (PMID 34853447, 2022).
liver disease (continued). "IL-1β, TNF-α, and IP-10 post-HKEB stimulation and IP-10 post-LPS stimulation negatively correlated with biochemical markers of liver disease severity and liver disease severity scores." (PMID 35195033, 2022). "In liver disease, CYLD acts as an important regulator of hepatocyte homeostasis by preventing progressive fibrosis, inflammation, tumor necrosis factor (TNF) production, and expansion of hepatocyte apoptosis towards the central veins." (PMID 35579924, 2022). "It seems that exercise and probiotic supplements can be effective in down-regulating TNF-α and MCP-1 and improving liver disease." (PMID 36110559, 2022). "In the early phase of liver diseases, Kupffer cell-derived proinflammatory cytokines, including CCL2, IL-1β, IL-6, IL-23, and TNF-α, induce the migration of immune cells and HSCs and contribute to the development of a proinflammatory liver microenvironment." (PMID 36380016, 2022). "For example, IP10 and TNFα correlated with the albumin/globulin ratio (i.e., AGR) and a low AGR can be indicative of infection, liver disease, or malnutrition." (PMID 34067023, 2021). "Moreover, TNF-α may involve in executing the biological functions as diverse as inflammatory responses, hepatocellular proliferation, and apoptosis, and it is the latter that is a salient characteristic feature of many forms of liver disease." (PMID 35047538, 2021). "The proinflammatory cytokines IL-6 and TNF-α activate the transcription factors STAT3 and NF-κB, which if persistently stimulated can aggravate liver disease progression and HCC development." (PMID 32357520, 2020). "Patients on therapies inhibiting release of Tumor Necrosis Factor TNFα have been shown to have suppressed IgG-CTF autoantibodies while some cancer and liver disease patients have elevated values." (PMID 33511378, 2020). "Serum levels of inflammation related cytokines, including IL-6, 10, and TNF-α, tend to increase with the MELD score, which is related to the severity of liver disease." (PMID 29649247, 2018). "It was reported to decrease the production of cytokines including TNF-α and TNF-β via inhibiting NF-κB, and thus it likely possesses the prophylactic effect on liver diseases by anti-inflammatory effects." (PMID 27043533, 2016). "Tumor necrosis factor-alpha (TNF-α), regarded as a pro-inflammatory cytokine, is actively involved in regulation of portal hypertension and carcinogenesis." (PMID 25908103, 2015). "Multiple studies indicate that the blood level of TNF-α is increased in HCV patients and its level is positively correlated with HCV pathogenesis and the severity of liver diseases." (PMID 26023919, 2015). "The genotypes TNF-α–308GG – LT-α + 252AA and TNF-α–308GA – LT-α + 252AG were unfavorable with regard to liver disease development (both p < 0.05)." (PMID 23343370, 2013). "The weak effect of anti-TNF was seen when treatment was administered coincident with NC1 knockdown and prior to the onset of NPC liver disease." (PMID 20886067, 2010). "In liver diseases, signaling pathways such as TLR4 and NF-κB activate endogenous cellular inflammatory vesicles, releasing pro-inflammatory cytokines like IL-1β, IL-6, and TNF-α." (PMID 39936090, 2025). "People with reduced muscle strength have elevated inflammatory markers such as Interleukin (IL)-1β, IL-6, Tumor Necrosis Factor-α (TNF-α), and high-sensitivity C-reactive Protein (hs-CRP), suggesting the close relationship between muscle mass impairment and liver diseases." (PMID 41373697, 2025). "However, key signal(s) that restrict abnormal TNF/TNFR activation in liver under physiological conditions and if and how alterations of these signals contribute to development and progression of inflammatory liver diseases are incompletely understood." (PMID 36622102, 2023).
liver disease (continued). "This also suggested that the major factor associated with the rise in serum IL-8 levels in patients with cirrhosis was the progression of hepatic failure, and/or increased stimulation by TNF-a, rather than the presence of portal hypertension alone." (PMID 35295601, 2022). "KEGG enrichment analysis indicated that 111 terms were related to liver disease, including cancer pathway, PI3K/Akt signaling pathway, non-alcoholic fatty liver disease (NAFLD), MAPK signaling pathway, HIF-1 signaling pathway, and TNF signaling pathway." (PMID 35795275, 2022). "Our results show that, after hepatic I/R injury, hepatorenal syndrome rapidly develops in rats, characterized by an increase in MMP-9-dimer and inflammatory changes such as an increase in renal cortex TNF-alpha, thus suggesting a key role for this pro-inflammatory cytokine in MMP activation." (PMID 35631351, 2022). "IFX was associated with a higher rate of induced liver disease compared with ETA, while no comparisons were possible with the other anti-TNF-α agents for the paucity of cases." (PMID 30060508, 2018). "In this review, we explored the hepatic safety concerns in patients receiving anti-TNF-α agents with and without pre-existent hepatic diseases." (PMID 30060508, 2018). "Although the link between oxidative stress and TNF-α production is well established in alcoholic liver disease, it is still not clearly determined in case of HCV-associated liver disease." (PMID 27293514, 2016). "TNF-α is involved in cellular injury and is thought to be a critical factor of inflammatory damage in liver diseases including viral hepatitis, alcoholic liver disease, nonalcoholic fatty liver disease, and ischemia-reperfusion injury." (PMID 27043523, 2016). "TNFα also modulates several matrix metalloproteinases that are involved in liver injury, repair, and remodeling, with MMP1 and MMP9 the most relevant MMPs with regards to liver disease." (PMID 26506376, 2015). "For instance, whereas a significant increase in the production of IL-1β, IL-6, IL-12, and TNFα was observed in chronic alcoholics without liver disease, chronic alcoholics with liver disease who were drinking alcohol showed low production of IL-1β and TNFα." (PMID 25762940, 2015). "The pathogenesis of multi-organ chronic inflammation in Sharpincpdm/cpdm mice depends on TNF, as double Sharpincpdm/cpdm;Tnf−/− mice did not develop signs of inflammatory skin and liver disease." (PMID 25443631, 2014). "Our study showed that TIPS does not influence the TNFα system in patients with liver cirrhosis and portal hypertension." (PMID 24386183, 2013). "Nevertheless, recent studies in patients with other forms of inflammatory liver diseases have not shown benefit of anti-TNF agents or IL-10, and the use of any of these agents would likely increase the risk of infections." (PMID 24386086, 2013). "Though other liver diseases have been associated with increased circulating TNF-α level, we did not observe unusually elevated TNF-α among our three patients with hepatic sarcoidosis and two patients with positive hepatitis C virus infection." (PMID 22195005, 2011). "Therefore, blockade of TNFα might represent a novel therapeutic target in NASH with the potential to limit tissue injury and possibly prevent the progression to severe liver disease." (PMID 37377968, 2023). "Collectively, our findings identify AF6 as a novel regulator of hepatocyte necroptosis, emphasizing the critical role of AF6 in sensitizing fatty liver deposits to TNFα-induced necroptosis, suggesting that AF6 may serve as therapeutic target for the prevention of necroptosis-related hepatic disease." (PMID 37828052, 2023). "In the evaluation of TNF-alpha and PG-PS IgAlevels and the hepatorenal ultrasound relationship, the values obtained in the studywere compared to those of infant populations without liver diseases." (PMID 32876312, 2021).
liver disease (continued). "Increased expression of 2B4 on hepatic CD8 T cells was also described for other liver diseases such as chronic hepatitis B and chronic hepatitis C and their blockade yielded in an increased CD8 T cell toxicity with proliferation and the secretion of inflammatory cytokines like IFN-γ and TNFα." (PMID 30949049, 2019). "Thus, the lack of TNF appeared to slow the progression of NPC liver disease." (PMID 20886067, 2010). "PBC patients have been reported to have higher serum levels of gut endotoxins/lipopolysaccharide, with increased expression of toll-like receptor (TLR) 4 and pro-inflammatory cytokines TNF-α, IL-1β, IL-6, and IL-8 compared to non-PBC liver disease." (PMID 39859319, 2025). "Thus, MMP-2, MMP-9 and TNF-α could not be correlated with the progression of liver disease." (PMID 26464613, 2015). "Targeting TNF-α mediated inflammation is not expected to halt the primary lysosomal lipid accumulation, but it may reduce secondary consequences of NPC liver disease." (PMID 20886067, 2010). "Circulating levels of TNF-α and TNF-R1 are higher in patients with alcoholic steatohepatitis than in heavy drinkers with inactive cirrhosis, heavy drinkers who do not have liver disease, and individuals with neither alcoholism nor liver disease." (PMID 20827314, 2010). "However, TNF-α induction in liver disease is by no means unique to chronic hepatitis C. Other types of liver infection and inflammation such as chronic hepatitis B and alcoholic hepatitis, which have no significant prevalence with T2DM, also induce TNF-α." (PMID 22675572, 2012).
sarcoidosis (258 papers, 1992 to 2026). Sarcoidosis is a multisystemic disorder of unknown cause characterized by the formation of immune granulomas in involved organs. "Serum TNF-α levels are linked to an endotype of the disease characterized by radiologically progressive sarcoidosis with impaired pulmonary function and exercise ability impairment." (PMID 40002701, 2025). "Increased expression of IL-2 and TNF-α has been associated with chronic active sarcoidosis and reduced expression with Löffler syndrome." (PMID 40002701, 2025). "The activation of alternative immune pathways in response to anti-TNF agents can lead to the onset of sarcoidosis in predisposed individuals." (PMID 40351964, 2025). "Conversely, G908R has been linked to enhanced IL-8 and TNF-α production in familial sarcoidosis, despite reduced NF-κB signaling, pointing to macrophage-driven chronic inflammation." (PMID 41357180, 2025). "TNF-α polymorphisms (308AA and rs1800629) are associated with both increased risk of sarcoidosis and pulmonary disease progression, while a IL-23 polymorphism (rs12069782) increases sarcoidosis risk but appears to protect against pulmonary disease progression." (PMID 40002701, 2025). "Increased lymphocyte counts during TNFi treatment suggests that TNF-α signaling is of importance for sarcoidosis associated lymphopenia." (PMID 40205574, 2025). "Immune checkpoint inhibitors, highly-active antiretroviral therapy interferons, and tumor necrosis factor (TNF-α) antagonists are the pharmacological classes most frequently linked to these drug-induced sarcoidosis-like reactions (DISRs)." (PMID 39110261, 2024). "A rare association between sarcoidosis and Crohn’s disease is reported, and additional targeted therapy against tumor necrosis factor-α and integrins is associated with the induction of sarcoidosis when used to treat inflammatory bowel disease." (PMID 39338270, 2024). "Sarcoidosis patients undergoing immunosuppressive therapy, especially with corticosteroids or TNFα blockers, are at increased risk of developing tuberculosis." (PMID 38256476, 2024). "On the other hand, etanercept, which is more commonly linked to sarcoidosis-like reactions, forms less stable complexes that can dissociate and allow the release of TNF-α." (PMID 37483590, 2023). "In this context, we think that our finding of an association with PB lymphopenia and HLA-DRB1*07 is interesting as genetic polymorphism of the TNF-α gene has been connected to HLA-DRB1 variants and response to TNF-α inhibitor treatment in sarcoidosis." (PMID 37161980, 2023). "The use of TNF inhibitors in sarcoidosis is also linked with a significant risk of adverse effects, most commonly infections and allergic reactions." (PMID 37334374, 2023). "A recent WHO pharmacovigilance review reported 2,425 cases of drug-induced sarcoidosis and strong associations with TNF-a antagonists, interferon, pegylated interferon, and immune checkpoint inhibitors." (PMID 37250639, 2023). "Blood monocytes from patients with sarcoidosis show reduced expression of CD200R which is linked to enhanced TNF and IL-6 production following PHA stimulation." (PMID 34868074, 2021). "Current therapies for sarcoidosis focus primarily on pharmacologically limiting inflammation, and include corticosteroids, immunosuppressants and anti-TNF-α agents, which are all associated with variable response and important side effects." (PMID 34769145, 2021). "The increased exercise tolerance, higher HDL levels and reduced AIP values and cytokines (TNF-α and IL-6) in response to exercise training suggested a positive effect of the rehabilitation program on cardiovascular risk in sarcoidosis patients." (PMID 33692469, 2021). "In sarcoidosis, PPARγ activity is deficient in AMs, leading to an increase in the production of TNFα, IL-12, and MMPs, which cause lung damage and fibrosis and induction of T-cell chemotaxis." (PMID 32722050, 2020).